SKP2 (S-phase kinase associated protein 2)
Diseases named in the same sentence as SKP2 in open-access papers (continued):
Sharing a sentence is not in itself a finding about the gene and the disease.
glioma (16 papers, 2012 to 2025). A benign or malignant brain and spinal cord tumor that arises from glial cells (astrocytes, oligodendrocytes, ependymal cells). "Studies have shown that in the treatment of glioma, curcumin plays a vital part in the treatment of tumors by downregulating the S-phase kinase associated protein 2 pathway in glioma cells." (PMID 37398678, 2023). "Skp2 overexpression has been implicated in tumorigenesis and has been associated with multiple human cancers, including gliomas." (PMID 33322413, 2020). "Another study discovered that 31 restrains glioma cell growth, movement, and infiltration and provokes G2/M phase arrest and apoptosis by modulating Skp2 expression within these cells." (PMID 40076568, 2025). "In this study, Skp2 expression was found to be upregulated in glioma, and high-level of Skp2 predicted poor prognosis for patients with LGG." (PMID 32165861, 2020). "Complete dependence on SKP2 also show human glioma M059K cells, while human embryonic kidney (HEK) 293 cells show a marked but incomplete inhibition of resection upon SKP2 knockdown." (PMID 32683422, 2020). "We then modulated Skp2 level by knockdown or small molecule inhibition, and then examined the functions of Skp2 in the development of glioma through in vitro and in vivo assays." (PMID 32165861, 2020). "Repression of Skp2 induced senescence in glioma cells as reported in nasopharyngeal carcinoma (***p < 0.01)." (PMID 32165861, 2020). "In this study, we demonstrated that Skp2 increased with glioma grade and predicted a poor prognosis in diffuse glioma as well as LGG." (PMID 32165861, 2020). "The Skp2 suppression delayed cell proliferation, sphere formation, and tumorigenesis, while the enhancement of Skp2 increased stem cell markers Nestin and Sox2 in glioma." (PMID 32165861, 2020). "In this study, we analyzed data from database to elucidate the role of Skp2 in clinical progression of glioma." (PMID 32165861, 2020). "In this way, we demonstrated that the Skp2 knockdown sensitized glioma cells to TMZ both in vitro and in vivo." (PMID 32165861, 2020). "The overexpression of BMPR1B activated the BMPs/Smad1/5/8 signaling pathway and inhibited the growth of glioma cells through various mechanisms, including the decrease of SKP2 expression, followed by the increase of p21 and p27kip1 Protein Expression35." (PMID 33116227, 2020). "Repurposing of lovastatin and novel compound SZL-P1-41 suppressed Skp2 effectively, and enhanced glioma cell sensitivity to TMZ in vitro and in vivo." (PMID 32165861, 2020). "To investigate the role of Skp2 in the prognosis of patients with glioma, we first analyzed data in databases TCGA and GTEx." (PMID 32165861, 2020). "First, we examined the efficiency and specificity of the Skp2 LOF approach in C6 glioma cells, where Skp2 siRNA lentivirus-mediated transduction led to a reproducible decrease in Skp2 protein and transcript levels, compared to controls." (PMID 27011052, 2016). "To determine the molecular mechanism of curcumin-mediated anti-tumor activities, we measured the expression of Skp2 at mRNA and protein levels in glioma cells treated with curcumin." (PMID 26046466, 2015). "In this study, our results demonstrated that curcumin inhibited Skp2 expression in glioma cell lines." (PMID 26046466, 2015). "Mechanistically, our findings demonstrated that curcumin exerts its anti-tumor functions through down-regulating Skp2 expression in glioma cells." (PMID 26046466, 2015). "More importantly, our Western blotting analysis showed that curcumin also down-regulated the Skp2 protein level in both glioma cells." (PMID 26046466, 2015). "Multiple studies have demonstrated that Skp2 has an essential oncogenic function in the pathogenesis of glioma." (PMID 26046466, 2015). "Furthermore, another study indicates that 51 restrains the growth, movement, and infiltration of glioma cells, and it influences glioma suppression by modulating the Skp2-p21-p27 signaling pathway." (PMID 40076568, 2025).
glioma (continued). "Skp2 is highly expressed in glioma cell lines compared to normal astrocyte cell lines; this could explain the differences observed between NHAs versus SVGAs and NHA-Ts." (PMID 34831441, 2021). "Our results therefore reveal the important role of Skp2 in glioma tumorigenesis, targeting Skp2 could potentially improve the therapeutic efficiency of glioma patients." (PMID 32165861, 2020). "Skp2 mRNA level was higher in both low-grade glioma and GBM than normal brain tissues." (PMID 32165861, 2020). "Through repression of Skp2, physcion 8-O-β-glucopyranoside, escitalopram oxalate, curcumin, butylidenephthalid blocked cell cycle, inhibited proliferation, induced apoptosis, therefore attenuated the cell viability of glioma cells or in mice models." (PMID 32165861, 2020). "Although it was reported that Skp2 could promote cell growth, migration, and invasion in glioma cells, the detailed function of Skp2 remains unclear." (PMID 32165861, 2020). "An increase of Skp2 promoted cell growth, migration, and invasion in glioma cells." (PMID 32165861, 2020). "Our results demonstrated that Skp2 was critically involved in glioma tumorigenesis and that curcumin down-regulated the expression of Skp2, resulting in upregulation of p57 and down-regulation of pAkt, which could lead to inhibition of tumorigenesis." (PMID 26046466, 2015). "Furthermore, we observed that overexpression of Skp2 promoted cell growth, migration, and invasion, whereas depletion of Skp2 suppressed cell growth, migration, and invasion and triggered apoptosis in glioma cells." (PMID 26046466, 2015). "Consistently, our invasion assay showed that Skp2 promoted cell invasion in both glioma cells." (PMID 26046466, 2015). "We observed that over-expression of Skp2 promoted cell growth in both glioma cell lines." (PMID 26046466, 2015). "Collectively, our findings suggest that targeting Skp2 by curcumin could be a promising therapeutic approach for glioma prevention and therapy." (PMID 26046466, 2015). "Due to oncogenic function of Skp2 in glioma, inactivation of Skp2 could be a promising strategy for the treatment of glioma." (PMID 26046466, 2015). "To further validate the inactivation of Skp2 by curcumin could impact on Skp2 downstream target genes such as pAkt and p57, we detected the expression of pAkt and p57 in glioma cells with curcumin treatment." (PMID 26046466, 2015). "Targeting Skp2 might improve the therapeutic effects of glioma patients." (PMID 32165861, 2020). "Thus, Skp2 was important in glioma cell proliferation in vitro and in vivo." (PMID 32165861, 2020). "Therefore, targeting Skp2 could be a promising strategy to improve therapeutic efficiency for glioma patients." (PMID 32165861, 2020). "Moreover, we explored whether curcumin exhibits its anticancer activity via inactivation of Skp2 in glioma cells." (PMID 26046466, 2015). "Next, we explored whether Skp2 could control cell motility in glioma cell lines." (PMID 26046466, 2015). "Notably, we identified that depletion of Skp2 suppressed migration and invasion in glioma cells." (PMID 26046466, 2015). "Importantly, overexpression of BMPR-IB activated the BMPs/Smad1/5/8 signaling pathway and clearly inhibited the growth of glioma cells through multiple mechanisms, including decreased expression of Skp2, and subsequently increased the expression of the p21 and p27Kip1 proteins." (PMID 22650359, 2012). "In this study, we investigated the function of Skp2 in the proliferation, stem cell maintenance, and drug sensitivity to temozolomide (TMZ) of glioma." (PMID 32165861, 2020). "Knockdown of Skp2 has been shown to increase sensitivity of gliomas to TMZ, attenuate growth of glioma cells and induce senescence in glioma cells." (PMID 33322413, 2020). "In other studies, the activity of ADAR2 was deemed essential to prevent glioma proliferation and growth through the editing of the CDC14B pre-mRNA transcript involved in the Skp2/p21/p27 pathway." (PMID 32375856, 2020).
glioma (continued). "As ADAR2 activity decreases in gliomas, CDC14B pre-mRNA modification is decreased, resulting in overexpression of Skp2 and downregulation of the known tumor suppressors p21 and p27." (PMID 32375856, 2020). "We previously reported that Skp2 is involved in self-renewal ability of hematopoietic stem cells and cancer stem cells in nasopharyngeal carcinoma, therefore we speculated that Skp2 modulated glioma stem-like cells and thereafter regulated cell proliferation and drug sensitivity." (PMID 32165861, 2020). "The S-phase kinase protein 2 (Skp2), a critical component of the E3-ligase SCF complex, has been documented in tumorigenesis in various cancer types but its role in glioma has yet to be fully clarified." (PMID 32165861, 2020). "We also demonstrated that the downregulation of Skp2 led to the retardation of cell proliferation, increased TMZ sensitivity, reduced the sphere formation ability of glioma stem-like cells, and enhanced cellular senescence." (PMID 32165861, 2020). "In support of this note, we observed that Skp2 increased Akt activation in U251 and SNB19 glioma cells." (PMID 26046466, 2015). "Therefore, inactivation of Skp2 could block development and progression of glioma." (PMID 26046466, 2015). "Our data demonstrated that Skp2 modulated glioma cell proliferation in vitro and in vivo, stem cell maintenance, and cell sensitivity to TMZ, which indicated that Skp2 could be a potential target for long-term treatment." (PMID 32165861, 2020). "To test whether Skp2 affects the cell sensitivity to TMZ, the common clinical chemotherapeutic reagent for glioma, we treated Skp2-knockdown cells with TMZ." (PMID 32165861, 2020). "Due to non-toxic nature, inhibiting Skp2 by nature agents could be a safer approach for treating glioma." (PMID 26046466, 2015).
cervical carcinoma (14 papers, 2007 to 2025). A carcinoma arising from either the exocervical squamous epithelium or the endocervical glandular epithelium. "Our study in a well-documented series of cervical cancer patients primarily treatment with radiotherapy reveals that higher SKP2 immunostaining is associated with poor DFS (P < 0.001), especially locoregional recurrence." (PMID 27317767, 2016). "Tumor samples were collected to examine the association between the expression of S-phase kinase-associated protein 2 (SKP2) and prognosis in cervical cancer." (PMID 27317767, 2016). "Together, these results suggest that SKP2 overexpressing cells showed increased cell survival and lower expression of SKP2 or loss of SKP2 activity in cervical cancer cells associated with lower survival fraction after irradiation." (PMID 27317767, 2016). "Next, Western blotting analysis was performed to investigate the association between SKP2 protein expression and radiosensitivity in HeLa cells and C33A cells that were previously characterized as radioresistant and radiosensitive cervical cancer cells, respectively." (PMID 27317767, 2016). "The patients with high expression of SKP2 cervical cancer are at high risk of locoregional recurrence and might be appropriate for adjuvant hysterectomy after radiotherapy." (PMID 27317767, 2016). "Meantime, Skp2 regulation at both translational and post-translational levels in breast and cervical cancers via this signaling pathway was also observed." (PMID 29566713, 2018). "SKP2-C25, an inhibitor for SKP2 activity, dose-dependently decreased cell viability after irradiation and knockdown of SKP2 impaired DNA-damage response and sensitized the cervical cancer cells to irradiation." (PMID 27317767, 2016). "High expression of SKP2 of tumor predicts higher locoregional recurrence of cervical cancer after radiotherapy." (PMID 27317767, 2016). "Together, these results suggested that SKP2 significantly increased the response of cervical cancer cells to efficiently repair DNA damage by irradiation." (PMID 27317767, 2016). "In conclusion, we found for the first time that high expression of SKP2 was correlated with poor response of radiotherapy and prognosis of cervical cancer." (PMID 27317767, 2016). "This study is the first to report that higher level of immunostaining of SKP2 predicts poor response to radiotherapy in cervical cancer." (PMID 27317767, 2016). "The results implied the cervical cancer cells with high expression of SKP2 had high radioresistant ability." (PMID 27317767, 2016). "In agreement with previous report, we found that a high expression of SKP2 in cervical cancer was correlated with higher stage, poorer differentiation, larger tumor size and deeper of invasion." (PMID 27317767, 2016). "Cervical cancer cell lines with higher expression of SKP2 showed higher colony formation, cell survival rate and fewer DNA damages after irradiation." (PMID 27317767, 2016). "Moreover, we evaluated the expression of cell cycle-related genes (CCNA2, MCM2 and SKP2) in cervical cancer cells transfected with siNC or siACTL6A." (PMID 34395295, 2021). "Due to the side effects of cisplatin, we aimed to investigate whether the SKP2 inhibitor may act as a radiosensitizer in cervical cancer, and with lower toxicity to normal cells." (PMID 27317767, 2016). "The expression patterns of SKP2 in cervical cancer tissues were correlated with clinicopathological variables including age at diagnosis, tumor stage, histological type, histological grade, tumor size, percentage of death and recurrence, recurrence site and the levels of SCC and CEA before therapy." (PMID 27317767, 2016). "Furthermore, we assessed the effect of SKP2 in the radiation response of cervical cancer cells in vitro." (PMID 27317767, 2016).
cervical carcinoma (continued). "We further investigated whether inhibition of SKP2 activity decreased cervical cancer cells survival after irradiation by SKP2-C25, an inhibitor of SKP2 that has been shown to selectively suppress SKP2 E3 ligase activity." (PMID 27317767, 2016). "Hence, recurrence, locoregional recurrence, death, larger tumor size, higher stage and poor differentiation occurred more frequently when cervical cancer in higher staining group for SKP2." (PMID 27317767, 2016). "SKP2 protein was shown in adenocarcinoma and squamous cell carcinoma of cervical cancer tissues." (PMID 27317767, 2016). "Targeting SKP2 may serve as a potential radiosensitizer for developing effective therapeutic strategies against cervical cancer." (PMID 27317767, 2016). "Next, we investigated whether the expression level of SKP2 in cervical cancer tissue before treatment could be a biomarker of recurrence after radiotherapy." (PMID 27317767, 2016). "Moreover, integrative genomics analysis and morphoproteomic evidence also identified target over-expressed genes, including SKP2 gene of chromosome 5p gain in cervical cancer may contribute to cervical dysplastic lesion progression to invasive tumor." (PMID 27317767, 2016). "Thus, upregulation of expression through amplification may be the case for TRIO, ANKH and SKP2 in some neoplasms, including cervical cancer, as indicated by our data." (PMID 17311676, 2007). "However, whether SKP2 play important roles on radiotherapy for cervical cancers remains obscure." (PMID 27317767, 2016). "We hypothesize that SKP2 may interact with MRN associated protein complex and trigger ubiquitination of these associated proteins upon DSBs, which is critical for facilitating ATM recruitment for DNA damage repair and improve radioresistance of cervical cancer cells." (PMID 27317767, 2016). "Our results also showed that SKP2 protein increased the ability of clearance of DSBs induced by irradiation in cervical cancer cell lines with decreasing Gamma-H2AX foci number and expression level in SKP2 overexpressing cells after irradiation." (PMID 27317767, 2016). "Staining level of SKP2, histologic types, SCC level, CEA level, and FIGO stage were confirmed to be independent prognostic factors of recurrence in cervical cancer." (PMID 27317767, 2016). "Elevated expression of RCC1 has been observed in cervical cancer, colon cancer, and soft tissue sarcoma, where RCC1 may play important role in nucleo-cytoplasmic trafficking of certain molecules such as Skp2 to regulate cell cycle transition and proliferation." (PMID 41391757, 2025).
liver cancer (14 papers, 2014 to 2024). An epithelial or non-epithelial malignant neoplasm that arises from the liver. "Furthermore, in vitro data suggest that hepatitis B virus (HBV) core promoter mutations might contribute to HBV associated liver cancer development by SKP2-dependent degradation of the p21WAF1 tumor suppressor gene." (PMID 25537506, 2015). "Using human HCC cell lines and mouse models of hepatocarcinogenesis, we revealed that SKP2 is a FASN downstream effector in liver cancer driven by AKT." (PMID 39064589, 2024). "Using liver cancer cell lines, mouse models, and human specimens, we found that SKP2 is a critical effector of FASN in this aggressive tumor." (PMID 39064589, 2024). "Of note, high expression of FoxM1 and its downstream effector factors (Plk1, CyclinB1, Skp2 and Aurora B Kinase) correlated with poor overall survival in hepatic cancer patients (analyzed from RNA-seq data available on Kaplan-Meier plotter)." (PMID 34900697, 2021). "In particular, virtually all the functional studies on SKP2 in liver cancer have been performed in vitro using HCC cell lines to date." (PMID 25537506, 2015). "In summary, our results provided evidence, for the first time, that BBR could induce growth inhibition and cell cycle arrest through the Akt/FoxO3a/Skp2 axis in Huh-7 and HepG2 liver cancer cells." (PMID 29360760, 2018). "Upregulation of SKP2 and its partner, CDC28 protein kinase regulatory subunit 1B (CKS1B), has been shown to be associated with a dismal prognosis and unconstrained tumor proliferation in liver cancer." (PMID 25537506, 2015). "In addition, it has been shown that SKP2 nuclear accumulation directly correlates with clinical aggressiveness of HCC and is associated with shorter survival of liver cancer patients." (PMID 25537506, 2015). "Furthermore, we found that SKP2 is one of the genes downregulated by the FASN inhibitor TVB3664 in in vitro and in vivo models of liver cancer." (PMID 39064589, 2024). "Thus, it is conceivable that novel therapeutic strategies combining SKP2 inhibitors with AKT/mTOR and Ras/MAPK inhibitors might be highly beneficial for the treatment of human liver cancer." (PMID 25537506, 2015).